ZNF248 (zinc finger protein 248)
Description:
May be involved in transcriptional regulation.
Synonyms: bA162G10.3
Tractability: PROTAC: UniProt records ubiquitination sites on it; ubiquitination databases record sites on it.
Gene: Protein-coding gene on chromosome 10 (37,776,526 to 37,858,107, reverse strand). Ensembl gene ENSG00000198105.
Subcellular location: Nucleus
Subcellular location (Human Protein Atlas): Nucleoplasm
Pathways (Reactome):
Gene expression (Transcription): Generic Transcription Pathway
Gene Ontology:
Molecular function: protein binding; DNA-binding transcription factor activity, RNA polymerase II-specific; RNA polymerase II transcription regulatory region sequence-specific DNA binding
Biological process: regulation of transcription by RNA polymerase II; regulation of DNA-templated transcription
Cellular component: nucleus; nucleoplasm
Genetic constraint (gnomAD): Loss-of-function variants: 20 observed, 46.07 expected, observed/expected ratio (o/e) 0.43, 90% interval 0.3 to 0.63. The upper end of that interval is the gene's LOEUF score, 0.63, which puts it in group 2 of 6, group 1 being the genes least tolerant of losing a copy. Missense variants: 654 observed, 713.82 expected, observed/expected ratio (o/e) 0.92, 90% interval 0.86 to 0.98. Synonymous variants: 224 observed, 241.78 expected, observed/expected ratio (o/e) 0.93, 90% interval 0.83 to 1.03.
Homologues: Orthologues: chimpanzee ZNF248 (99% identical), macaque ZNF248 (97% identical), pig ZNF248 (86% identical), rabbit ZNF248 (84% identical), dog ZNF248 (83% identical), guinea pig ZNF248 (80% identical), mouse Zfp248 (75% identical), rat Zfp248 (75% identical), Drosophila melanogaster CG3281 (23% identical), Drosophila melanogaster Phs (19% identical), Drosophila melanogaster CG2712 (19% identical). Paralogues in human: ZFP37 (37% identical), ZFP90 (37% identical), ZNF674 (36% identical), ZNF25 (36% identical), ZNF614 (36% identical), ZNF875 (35% identical), ZNF10 (34% identical), ZNF20 (34% identical), ZNF529 (34% identical), ZNF805 (34% identical), ZNF599 (34% identical), ZNF560 (34% identical), and 50 more.
Diseases named in the same sentence as ZNF248 in open-access papers:
ZNF248 is named in the same sentence as 8 diseases in open-access papers, as found by Europe PMC text mining. Sharing a sentence is not in itself a finding about the gene and the disease. The quoted sentences say what the papers report.
colon cancer (1 paper, 2024). "Furthermore, ZNF248 was found to bind to ZEB1 in two colon cancer cells using IP assays." (PMID 39247604, 2024).
colorectal cancer (1 paper, 2024). A primary or metastatic malignant neoplasm that affects the colon or rectum. "Collectively, these data imply that ZNF248 plays a pivotal role in promoting the mesenchymal-epithelial transition of colorectal cancer, ultimately regulating the occurrence of liver metastasis in CRC." (PMID 39247604, 2024).
lymph node metastasis (1 paper, 2024). "Immunohistochemical analysis indicated a substantial association of ZNF248 expression with the lymph node metastasis, and with the liver metastasis (P =0.01, P =0.01), and a positive correlation between ZNF248 and ZEB1 expression (P =0.021) was also identified." (PMID 39247604, 2024).
cancer (1 paper, 2024). A tumor composed of atypical neoplastic, often pleomorphic cells that invade other tissues. "Both qRT-PCR and IHC results confirmed that ZNF248 expression was elevated in cancer tissues, closely associated with lymph nodes and distant metastasis (p=0.01)." (PMID 39247604, 2024). "Consistent with bioinformatic data, a high expression level of ZNF248 was observed in cancer tissue." (PMID 39247604, 2024). "By analyzing 100 CRC patient tissues, it is found that ZNF248 is highly expressed in cancer tissue as well as in CRC cell lines identified by qRT-PCR." (PMID 39247604, 2024). "ZNF248 expression among various human cancers was next assessed." (PMID 39247604, 2024).
tumor (1 paper, 2024). "Using bioinformatics tools, we analyzed the TCGA-COAD and GES146587 datasets and identified ZNF248 participating in tumor progression." (PMID 39247604, 2024).
ZNF248 also shares sentences with these, for which no sentence is quoted: colorectal tumor (1 paper); genetic diseases (1); Parkinson disease (1).